IL6 (interleukin 6)
Diseases named in the same sentence as IL6 in open-access papers (continued):
Sharing a sentence is not in itself a finding about the gene and the disease.
tumor (continued). "Further studies identified that PLXNC1 promoted GC proliferation in vitro and in vivo, as well as migration in vitro by activating tumor-related pathways such as the IL-6/STAT3 signaling pathway." (PMID 32117710, 2020). "The production of cytokines, including CCL2 and IL-6, which are important in promoting tumor growth, is significantly inhibited by trabectedin in four different mouse tumor models." (PMID 32260363, 2020). "TNF-α, IL-6, and IL-17 have known roles in tumor growth and promotion; IL-6 and IL-10 are produced by tumor-associated macrophages and create conditions of immune suppression and angiogenesis." (PMID 32156252, 2020). "In this complex scenario, CAF-derived IL-6 sustains tumor growth and invasion via EpMT of breast epithelial cells." (PMID 32604738, 2020). "For example, IL-6, IL-10 and VEGF, generally overexpressed in the TIME can stimulate STAT3-related pathway to induce an immature and tolerogenic phenotype in tumor-associated dendritic cells (TADCs), thereby boosting cancer progression." (PMID 33148302, 2020). "Mice deficient in the IL-1 receptor-related molecule SIGIRR show increased tumor growth, while tumor-infiltrating myeloid cells produce high levels of IL-1β and IL-6 that promote tumorigenesis." (PMID 32670290, 2020). "For example, the RhoA/ROCK signaling pathway has been found to participate in IL-6-mediated tumor invasion and distant metastasis." (PMID 33158289, 2020). "TNF-α and IL6 are important pro-inflammatory cytokines known to have pleotropic function in immune response, inflammation, cell death and tumor progression." (PMID 33123499, 2020). "Proinflammatory cytokine IL-6 is a primary cytokine in the tumor microenvironment, which is produced by macrophages, neutrophils, monocytes, tumor cells and other cell types 38-40." (PMID 32201532, 2020). "Researches have shown that RFA can lead to acute serologic elevation of active cytokines such as IL-6, nMDSC, and mMDSC, and a sustained high infiltration level of macrophages in the residual tumor." (PMID 32760707, 2020). "High expression of PLXNC1 manipulated IL6ST expression at the DNA level and activated tumor-related pathways such as the IL-6/STAT3 pathway." (PMID 32117710, 2020). "We further observed that the effect of IL6 was reverted upon silencing the IL6 receptor on tumor cells (by siRNA for IL6R) as well as upon inhibition of glucose transporters by STF31." (PMID 33177492, 2020). "Among these cytokines, IL-6 have been reported to play an important role in M2 macrophage polarization, which lead to formation of tumor microenvironment in various cancers." (PMID 32196489, 2020). "Specifically, tumor-derived lactate polarizes local myeloid cells toward an M2 phenotype, boosting IL-6 release." (PMID 32193527, 2020). "Taken together, these data confirmed the role of IL-6 from TME in the promotion of tumor invasion through upregulation of integrin β6 in CRC cells." (PMID 32855767, 2020). "Tumour cells can secrete platelet agonists to induce platelet aggregation, which results in thrombocytosis by producing thrombopoietic cytokines such as interleukin (IL)-1, IL-3, IL-11, and particularly tumour-derived IL-6." (PMID 32312252, 2020). "It has been reported that tumor-derived Jagged-1 activates Notch signaling and promotes bone metastasis, and upregulates IL-6 and TGF, which in turn promote tumor cells proliferation and survival 22,32,33." (PMID 32549768, 2020). "Tumor growth and plasma IL-6 levels were significantly decreased in mice receiving the ketogenic formula compared to tumor-bearing control." (PMID 33415123, 2020). "The observed ectopic expression of stemness genes in patient St23784/17 led to high proliferative activity of EpCam+ tumor cells and induction of mammospheres due to the EpCam+ tumor stem cell fraction under the influence of IL-6." (PMID 32523653, 2020).
tumor (continued). "Multiple cancer types have been found to secrete exosomes containing heat shock proteins, Hsp72 and Hsp90, which activate Stat3 in MDSCs via IL6 and promote immunosuppression and tumor growth." (PMID 32547552, 2020). "First, CSCs recruit MSCs to the sites of primary tumor growth by secreting IL-6, which also triggers other responses in the tumor niche." (PMID 33059744, 2020). "One study demonstrated that the IL-6/JAK/STAT3 pathway plays an important role in the tumor microenvironment and drug research." (PMID 32792945, 2020). "IL‐6 clearly plays an important role in the crosstalk between MSCs and the tumor microenvironment, and additional work is needed to elucidate the full spectrum of its effects." (PMID 31608444, 2020). "The direct or indirect induction of proinflammatory mediators, like IFNγ, IL4, IL6, IL13, VEGF, GM-CSF, CSF-1, Ang-2, CCL2 and other chemokines in the tumor milieu, has an antitumor effect linked to M1 polarization of TAM." (PMID 32708142, 2020). "The secretion of TNF-α, IL-6, and NO are elevated by M1 macrophages, which are typically described as tumor-killing macrophages." (PMID 32512803, 2020). "In breast cancer, tumor-derived Jag1 induces IL-6 secretion from osteoblasts, which feeds back to cancer cells to promote tumor growth." (PMID 32092942, 2020). "Recent studies have verified that reduced tumor growth is achieved via IL-6 and/or IL-8 cytokine signalling blockade." (PMID 32211043, 2020). "Along with the suppression of anti-tumor immunity, myeloid cells produce inflammatory cytokines (IL-23, IL-6, IL-1) that drive the expansion and activation of pro-tumorigenic T helper 17 (Th17) cells." (PMID 32962159, 2020). "As an essential proinflammatory mediator, interleukin-6 has been identified to promote oncogenesis by regulation of tumour cells survival, metabolism and angiogenesis." (PMID 33046024, 2020). "In a breast cancer mouse model, CXCR2+ MDSCs promoted tumor growth and metastasis by secretion of IL-6 and modulation of CD4+ and CD8+ T cell recruitment to the tumor site." (PMID 32509781, 2020). "Systemically, neutralization of IL-6 and G-CSF led to a decrease in the frequency of CD11b+Ly6C+Ly6G+ myeloid cells in the spleen and also reverted the tumor triggered inhibition of NFκB in antigen-presenting cells and T lymphocytes." (PMID 33330068, 2020). "UBC cells produce a variety of pro-angiogenic, pro-inflammatory cytokines, such as IL-1, CXCL-1 or IL-6, which accelerate tumour growth and metastasis formation in an auto- and paracrine manner." (PMID 33267794, 2020). "During the defense against tumors, immune cells produce pro-inflammatory cytokines such as TNF-α, IL-6, and IL-1β, and tumor-specific T cells produce perforin and granzyme B to clear tumor cells." (PMID 33299138, 2020). "M1 macrophages lead to adipose secretion of several pro-inflammatory cytokines, such as TNF-α, IL-1, and IL-6, contributing to affect the microenvironment of tumor growth." (PMID 31963221, 2020). "Using a combination of human tissues, xenografts, syngeneic mouse models, and canine models of disease, they have shown how a ΔNp63/IL6/CXCL8 signaling axis mediates tumor-host signaling events critical to the metastatic process." (PMID 32082995, 2020). "There were the most tumour nodules in IL‐6 administration group, and few tumour nodules were found in shTIM‐4 group." (PMID 32020709, 2020). "Further experiments suggested the IL-1α/IL-1R/MYD88/IL-6 pathway as responsible for the reduced anti-tumor efficacy of erlotinib and other EGFR inhibitors." (PMID 33115415, 2020). "Inflammatory mediators such as Hmgbl, IL-23 and IL-17 can promote tumor growth by activating the IL-6/STAT3 pathway in a mouse model of melanoma." (PMID 32283655, 2020). "Blockade of canonical Nuclear Factor Kappa-light-chain-enhancer of activated B cells (NF-κB) reduced the production of PGE2 and/or IL-6 by the tumor cells and abrogated the effect of the chemotherapy." (PMID 32656079, 2020).
tumor (continued). "To further evaluate crosstalk between Trichomicin and the tumor microenvironment in vitro, we investigated the ability of Trichomicin to reduce the expression and secretion of IL-6 and TNFα in macrophage-like differentiated THP1 cells." (PMID 32317968, 2020). "This study demonstrated that Jag1 expression by the tumor cells mediated their interactions with osteoblasts, promoting their ability to release IL-6 that elevated tumor cell proliferation." (PMID 32605277, 2020). "These include interleukin-6 (IL-6), which mediates autocrine and paracrine growth of MM cells and inhibits tumor cell apoptosis, as well as TGF-β, which is an immune inhibitory factor that induces IL-6 secretion." (PMID 32391000, 2020). "Neutrophils have been shown to secrete several chemokines and cytokines, such as transforming growth factor-beta, interleukin-6, interleukin-8, and so on, and these agents contribute to tumor development, progression, and metastasis." (PMID 32219142, 2020). "When bone metastasis occurs, osteoblasts in the bone microenvironment (BME) secrete calcineurin (CaN) and osteoprotegerin (OPG), and tumour cells secrete parathyroid hormone-related peptide (PTHrP) and interleukin- 6 (IL-6)." (PMID 32546271, 2020). "This implies a potential role of IL-6 and Wnt signaling pathways in the biology of tumor-infiltrating I-MDSCs." (PMID 31941522, 2020). "In this study, we evaluated the anticancer activity of Trichomicin in vivo, and found that it decreased the expression of IL-6 and TNFα in tumor tissues." (PMID 32317968, 2020). "Classically activated macrophages (M1) protect the body from external pathogens and destroy tumor cells by secreting the pro-inflammatory cytokines IL6, IL12, IL23, and tumor necrosis factor-α (TNF-α), as well as releasing reactive oxygen/nitrogen species." (PMID 32582698, 2020). "AR antagonist action results in appearance of NEPC tumour cells, but cytokines such as IL6 which are elevated in PCa patients can also directly induce NED in LNCaP cells." (PMID 32802517, 2020). "Th17 cells, arising from stimulation of transforming growth factor (TGF)-β and IL-6, play a significant part in inflammation and tumor development.The coprecursor cell of Th1 and Th2 is Th0 cells." (PMID 33144870, 2020). "In conclusion, γδ T cells are novel stimuli of PSC secreted IL-6 contributing to their role as critical regulators of immunosuppression and tumor progression in PDAC." (PMID 32865617, 2020). "Meanwhile, we detected that Stat3 was drastically activated only in tumor cells treated by IL-6-CM, and addition PP VII prior IL-6 in macrophages during preparing CM prevented the provocation, but not for STING-knockdown macrophages." (PMID 33288772, 2020). "Lines cultured with interleukin-6 showed significantly improved correlations with patient tumor (p = 9.5e−4)." (PMID 32123307, 2020). "IL-6 level was elevated in the culture supernatant of MDSCs from the tumour site, and IL-6 neutralising antibody partially inhibited IL-17 production by naïve T cells." (PMID 32973748, 2020). "AZD1480, a JAK1/2 inhibitor, exhibited antitumor activity by inhibiting the growth of ES cells and tumor formation in xenograft models via the suppression of the IL-6/JAK2/STAT3 signaling pathway." (PMID 32754598, 2020). "It has been shown that IL-6 is responsible for acute phase responses, T lymphocyte stimulation, and B lymphocyte proliferation and differentiation in neoplastic diseases." (PMID 33062717, 2020). "Additional experiments were performed to test the effects of remdesivir and VS-6766 or other MEKi on ACE2, TMPRSS2, and IL-6 in tumor and normal cell lines." (PMID 33245731, 2020). "Chemoresistance is associated with elevated levels of PGE2 and IL-6, two inflammatory mediators that are regulated by cyclooxygenase (COX), drive differentiation of monocytes to the M2 tumor-promoting phenotype." (PMID 32656079, 2020).
tumor (continued). "IL-6 is also a pro-inflammatory cytokine generated by fibroblasts, monocytes, lymphocytes and various tumor cells." (PMID 33244088, 2020). "Scholars have found that the inflammatory factor interleukin-6 (IL-6) and parathyroid hormone related proteins (PTHrP), secreted by tumour tissues, are closely relevant to the adipose tissue browning process." (PMID 32902340, 2020). "TAM-derived IL-6 has a pivotal role in tumor initiating, survival, proliferation, and drug resistance in solid tumors." (PMID 32982967, 2020). "A variety of studies have reported that malignant ascites contain a lot of tumor-promoting molecules, including exosomes and inflammatory cytokines such as interleukin (IL)-6, IL-8, IL-10, hepatocyte growth factor (HGF), TGFβ." (PMID 32230983, 2020). "IL-6 is another major tumor-promoting cytokine produced by both malignant and host cells within the tumor microenvironment." (PMID 32486470, 2020). "In a tumor microenvironment, in addition to the tumor cells themselves, various types of cells, which include tumor infiltrating immune cells, stromal cells and fibroblast, produced IL-6, and several factors can initiate this process." (PMID 32961987, 2020). "IL6-rich tumor microenvironment provided by systemic thermal therapy improves cytotoxic T cells’ delivery to tumor lesions in mouse tumors and patient tumor explants." (PMID 33381115, 2020). "JAK and ROCK signaling promote actomyosin contractility downstream IL-6 in the context of tumor cells and stromal fibroblast, but IL-23 signaling has not been previously linked to actin dynamics nor to cell migration." (PMID 32203518, 2020). "Among cytokines and chemokines induced by thermal stress, IL-6 plays a pivotal role in the tumor immune microenvironment." (PMID 33240283, 2020). "In tumors, CD47 can elevate the expression of macrophages and increase their phagocytosis through IL-6, which affects the clearance of tumor cells and has a great impact on the prognosis of tumor cells." (PMID 32733941, 2020). "Particularly, IL-6 has been reported to be one of the most important pro-tumor factors in HCC progression." (PMID 32123532, 2020). "As IL-6 secretion was showed to be most suppressed in the supernatant of HSCs with TU-100 treatment, we confirmed that anti-IL-6 antibody has the effect of tumor regression as well as TU-100." (PMID 33346211, 2020). "IL-6 stimulates tumour cell proliferation and survival through the inhibition of apoptosis and interference with IL-6R signalling leads to decreased UM cell viability." (PMID 33066024, 2020). "Despite the prominent role of IL-6 in tumour biology, this aspect of stromal biology seems to have been somewhat neglected until now." (PMID 33114676, 2020). "As previously commented, β2-AR on NSCLC inactivates LKB1, increases CREB activity, and enhances tumor-secreted IL-6." (PMID 32516941, 2020). "IL6 signaling plays an important role in tumor cell growth, survival, angiogenesis, immunomodulation of the tumor microenvironment, stromal cell activation, and cancer progression." (PMID 32957689, 2020). "Snail expressed tumor cells not only recruited macrophages by secreting cytokines such as CCL2, CCL5, and IL-6, but also secretes tumor-derived exosomes (TEXs) which contains miR-21 to induce M2-type polarization of macrophages." (PMID 33224886, 2020). "The addition of the Il-6 neutralizing antibody abrogated the increase in stromal Grem1 expression when OP9 cells were cultured with 5TGM1 tumor cells (p < 0.05)." (PMID 32756430, 2020). "Interleukin-6 (IL-6), one of the major cytokines in the tumor microenvironment, is involved in the host’s immune defense system and in the modulation of growth through an autocrine and paracrine secretion and differentiation." (PMID 32397183, 2020).
tumor (continued). "Previous studies showed that the IL-6/JAK-STAT3 pathway is abnormally hyperactivated in multiple tumor types and elevated expression of IL‐6 can stimulate hyperactivation of JAK/STAT3 signaling which usually leads to an unfavorable clinical outcome 43-45." (PMID 32742470, 2020). "More recently, it was demonstrated that interleukin-6 (IL-6), VEGF and monocyte chemo-attractant protein 1 (MCP-1) are actively secreted by cancer-associated fibroblasts, to induce tumor cell proliferation." (PMID 32521677, 2020). "In short GCTSCs contribution for tumor proliferation via promoting macrophages M2 phenotype polarization by improving IL-6 and IL-10 secretion." (PMID 32904108, 2020). "We evaluated the plasma concentrations of Th1 (IL-2, IFN-γ, and TNF-α), Th2 (IL-4, IL-5, IL-6, and IL-10), Th9 (IL-9), and Th17 (IL-17A, IL-17F, IL-21, and IL-22) cytokines in tumor-bearing mice by flow cytometry." (PMID 32802733, 2020). "STAT3 pathways are activated by some of these cytokines, and their activation of malignant cells stimulates their proliferation and survival; indeed, upregulating cytokines IL-1β and IL-6 promotes angiogenesis and tumor invasion." (PMID 32156252, 2020). "Recently, preclinical and clinical studies showed that IL-6 was strictly related to colon cancer; it stimulated colony formation of cancer cells in vitro and its suppression inhibited tumor growth in vivo." (PMID 32283655, 2020). "The most significant biological processes that appear to negatively correlate with the immune risk are IFN-α responses, IFN-γ responses, IL-2/STAT5 signaling and IL-6/JAK/STAT3 signaling, all of which were associated with tumor immunity." (PMID 31988638, 2020). "All together, these results suggested that GCAFs promote VM formation and tumor growth in GBC via upregulating NOX4 expression through paracrine IL-6 mediating IL-6/JAK/STAT3 signaling pathway." (PMID 33153467, 2020). "Among all immunosuppressive signals related to HCC tumor immunity, the NF-κB/IL-6/STAT3 inflammatory axis is crucial for promoting tumor proliferation and evasion, with protumor cytokines being highly upregulated by this pathway." (PMID 32595757, 2020). "This, along with neutrophil and macrophage-derived secretion tumor growth factors such as hepatocyte growth factor, IL-6, IL-8, and metalloproteases, the tumor microenvironment becomes stimulated." (PMID 33054830, 2020). "Studies have shown that STAT3 is a transcription factor for the S1PR1 gene, and enhanced expression of S1PR1 can continuously activate STAT3 and upregulate the expression of the IL-6 gene, thereby accelerating tumor growth and metastasis." (PMID 33101013, 2020). "In many tumors, IL-6 and its receptor IL-6R are highly expressed, and the high expression of IL-6 is closely related to the poor clinical prognosis of tumor patients." (PMID 32549792, 2020). "The cytokines TNF-α and IL-6 can induce tumor cell apoptosis and result in tumor necrosis, acting as critical roles in mediating the signal transduction which stimulates the immune defense system." (PMID 33126624, 2020). "It was reported that DCs with abnormal function in the tumor microenvironment can produce tumor promoting IL-6 and immunosuppressive galectin-1, which can impair the local anti-tumor immunity." (PMID 33240930, 2020). "GCAFs promote VM formation and tumor growth in GBC via upregulating NOX4 expression through the activation of IL-6-JAK-STAT3 signal pathway." (PMID 33153467, 2020). "The inhibition of IL-6 by the use of an IL-6 antagonist, tocilizumab, or through shRNA, resulted in decreased tumor growth, reduced cancer stem cells (CSCs), and the suppression of colony formation in HER2+ and TNBC studies." (PMID 32023849, 2020). "In this study, the impact of C‐26 tumor burden and treatment with AR‐42, GTx‐024, or combination therapy on a panel of circulating cytokines, including IL‐6, was assessed." (PMID 31930715, 2020).